KRT8P45 (keratin 8 pseudogene 45)
Gene: Processed pseudogene on chromosome 1 (157,073,257 to 157,074,703, forward strand). Ensembl gene ENSG00000224520.
Diseases named in the same sentence as KRT8P45 in open-access papers:
KRT8P45 is named in the same sentence as 2 diseases in open-access papers, as found by Europe PMC text mining. Sharing a sentence is not in itself a finding about the gene and the disease.
KRT8P45 shares sentences with these, for which no sentence is quoted: ovarian serous cystadenocarcinoma (1 paper); uterine corpus endometrioid carcinoma (1).